MSLN (mesothelin)
Diseases named in the same sentence as MSLN in open-access papers (continued):
Sharing a sentence is not in itself a finding about the gene and the disease.
mesothelioma (continued). "In conclusion, many tumors such as mesothelioma and ovarian serous carcinoma showed equal immunoreactivity with both 5B2 and MN-1 antibodies, however, differences in mesothelin expression were seen in other tumor types using 5B2 or MN-1 antibodies." (PMID 28460459, 2017). "We assessed the binding of Amatux-LPS and HN1-LPS BsAbs (anti-MSLN-LPS BsAbs) by performing flow cytometry analyses using two mesothelioma cell lines (H226 and MSTO-211H)." (PMID 29059207, 2017). "Sensitivity and specificity of mesothelin were 51.6 and 71.4%, 51.6 and 85.2%, and 51.6 and 85% for differentiating mesothelioma from metastatic cancers to pleura, other benign pleural diseases and benign asbestos pleurisy, respectively." (PMID 28335760, 2017). "Serum mesothelin levels have been found to correlate with mesothelioma responsiveness to anti-mesothelin therapies." (PMID 28460459, 2017). "We also tested the expression of MSLN in established human lung cancer cell lines (H460 and A549) and mesothelioma cell line (H2052)." (PMID 28288645, 2017). "When compared to normal (non-cancer) human lung epithelial cell line (BEAS-2B) and mesothelial cell line (MeT 5A), expression of MSLN was highly elevated in the cancer cell lines, suggesting a carcinogenic role of MSLN in lung cancer and mesothelioma." (PMID 28288645, 2017). "In this study, we investigated the role of MSLN in lung cancer and mesothelioma by evaluating the effects of MSLN knockdown and overexpression on tumor growth and metastasis in a mouse model." (PMID 28288645, 2017). "MPF is cleaved by furin and shed into systemic circulation, and has been evaluated as a more accurate biomarker, as compared to the mesothelin precursor for the immunodiagnosis of mesothelioma." (PMID 29113296, 2017). "The only useful biomarker for mesothelioma is mesothelin which is elevated in between 15 and 40 % of individuals exposed to asbestos before diagnosis of mesothelioma." (PMID 26807072, 2016). "Mesothelin expression was detectable on several mouse cancer cell lines: AB12 mesothelioma, TRAMP-C3 prostate adenocarcinoma, and the JWF2 keratinocyte squamous cell carcinoma." (PMID 26931187, 2016). "Mesothelin is a cell surface glycoprotein and tumor differentiation antigen expressed in several aggressive tumors namely, mesothelioma, pancreatic adenocarcinoma, ovarian cancer and lung adenocarcinoma." (PMID 26981775, 2016). "Mesothelin expression was observed by IHC in multiple patients with mesothelioma, head and neck, pancreatic adenocarcinoma, colorectal cancer, and biliary cancer." (PMID 25502863, 2015). "Mesothelin represents a good candidate, as it is expressed in virtually all mesotheliomas, and antibodies targeting this protein are the basis of several therapeutic approaches." (PMID 26125439, 2015). "The frequencies of patients with mesothelin expression were high in mesothelioma and pancreatic adenocarcinoma, consistent with prior reports." (PMID 25502863, 2015). "All tumors were positive (15-100% of tumor cells) for mesothelioma-related markers mesothelin and calretinin by IHC." (PMID 25952750, 2015). "Mesothelin is elevated in the blood and effusions of patients with mesothelioma, and is rarely elevated in people with benign disease with normal renal function." (PMID 25927434, 2015). "The serum mesothelin level was significantly elevated in mesothelioma patients as compared to normal healthy donors (p < 0.0001)." (PMID 25996440, 2015). "NCI-Meso18, which was derived from an epithelioid mesothelioma, retained moderate expression of calretinin and minimal expression of mesothelin and WT1." (PMID 25952750, 2015). "Tissue samples from 46 patients with solid tumors other than mesothelioma and pancreatic adenocarcinoma were assayed for IHC prior to enrollment because they were required by eligibility criteria to be mesothelin positive." (PMID 25502863, 2015).
mesothelioma (continued). "The 11-25 mAb was utilized in a sandwich ELISA for detecting soluble form of MSLN in sera of patients with mesothelioma." (PMID 25883990, 2015). "Soluble mesothelin is the most intensively investigated mesothelioma biomarker and has been approved by the US FDA primarily as a tool for monitoring patient response and progression." (PMID 25927434, 2015). "Patients with mesothelioma had consistently higher serum mesothelin levels than patients with pancreatic cancers." (PMID 25756664, 2015). "Amatuximab is a chimeric monoclonal antibody that targets mesothelin, which is expressed in virtually all mesotheliomas and pancreatic adenocarcinomas." (PMID 25502863, 2015). "We found that the average serum mesothelin level in mesothelioma patients was around 5 nM while its level in normal serum was below 2 nM." (PMID 25996440, 2015). "It localizes to mesothelin expressing cancers with a higher uptake in mesothelioma than pancreatic cancer." (PMID 25756664, 2015). "Bacterial immunotoxins have been used in clinical trials to successfully treat hematological malignancies and solid tumors, as well as used as an adjuvant therapy targeting mesothelin-expressing mesothelioma, ovarian, or pancreatic cancer." (PMID 24990559, 2014). "A Phase I trial was subsequently initiated, where mesothelin-positive and recurrent or unresectable mesothelioma, ovarian, or pancreatic cancer patients were infused with SS1P continually for ten days." (PMID 24990559, 2014). "Mesothelin level seems to correlate with MM disease bulk and can potentially predict relapse in patients who had previously resected mesothelioma." (PMID 25227779, 2014). "In summary, our data suggests that serum mesothelin assessment is a feasible and useful test for prognostication in mesothelioma in a routine clinical setting." (PMID 25227779, 2014). "MSLN is overexpressed in many types of cancers, including ovarian, pancreatic/biliary, lung cancers and mesotheliomas." (PMID 24520352, 2014). "Immunohistochemical stain for MSLN yielded uniform, strong cytoplasmic and membranous reactivity in the mesothelioma tumor cells used as positive control." (PMID 25506917, 2014). "The diagnosis of malignant mesothelioma in humans can be supported by staining for proteins commonly expressed in mesotheliomas, including calretinin, cytokeratins, mesothelin, WT-1 and podoplanin (D2-40)." (PMID 24405760, 2014). "Median mesothelin concentration for mesothelioma cases was 1.96 nmol/l (IQR 1.16–4.18 nmol/l) whereas for controls median concentration was 0.93 nmol/l (IQR 0.65–1.31 nmol/l)." (PMID 25469901, 2014). "Mesothelin concentration in plasma and miR-103a-3p levels in the cellular blood fraction were analyzed in 43 male mesothelioma patients and 52 male controls formerly exposed to asbestos." (PMID 25469901, 2014). "N-ERC/mesothelin is considered to be relevant in monitoring chemotherapeutic response in patients with mesothelioma." (PMID 25347530, 2014). "Several ongoing clinical trials in patients with ovarian cancer, with pancreatic cancer or with mesothelioma suggest that MSLN-specific T-cell responses have a beneficial effect." (PMID 25506917, 2014). "Soluble mesothelin (MSLN) has a history as a biomarker for mesothelioma diagnosis, prognosis and monitoring." (PMID 23590973, 2013). "Biochemical markers significantly associated with mesothelioma were hyaluronan (odds ratio, 95% CI: 8.82, 4.82–20.39), N-ERC/mesothelin (4.81, 3.19–7.93), CERC/mesothelin (3.58, 2.43–5.59) and syndecan-1 (1.34, 1.03–1.77)." (PMID 23991032, 2013). "The most studied soluble mesothelioma marker to date is the C-ERC/mesothelin fragment: in pleural effusions the AUC span from 0.72 to 0.88 in various studies, however, most studies lack external validation." (PMID 23991032, 2013). "In the subjects with mesothelioma, there was a significant correlation between the serum and pleural fluid mesothelin levels (Spearman’s rho = 0.632, p<0.001)." (PMID 23009708, 2012).
mesothelioma (continued). "We assessed the expression of a known mesothelioma marker, MSLN, and found a robust expression of the gene in both MPeMSCs and parental MPeM cells." (PMID 23285196, 2012). "The derived MPeMSCs show significant expression of MSLN, a prominent marker for mesothelioma indicating that CSCs originated from the parental mesothelioma cells." (PMID 23285196, 2012). "Mesothelin is a glycoprotein overexpressed by mesothelioma and measurements in pleural fluid and serum are significantly higher compared to non-mesothelioma MPEs and benign effusions." (PMID 23009708, 2012). "In mesothelioma, preclinical studies targeting mesothelin with immunotoxins CAT-5001 (formerly SS1P) and amatuximab (previously known as MORab-009) were promising and therefore progressed to clinical trials." (PMID 22778767, 2012). "Mesothelin, a differentiation antigen present in a series of malignancies such as mesothelioma, ovarian, lung and pancreatic cancer, has been studied as a marker for diagnosis and a target for immunotherapy." (PMID 22485139, 2012). "Nonetheless, our data demonstrate that pleural fluid DNA integrity index is comparable in sensitivity to pleural fluid and serum mesothelin in diagnosing mesothelioma." (PMID 23009708, 2012). "To confirm the specificity of these markers in human mesothelium and mesothelioma we designed primers against human MSLN, UPK3B, NKAIN4 and LRRN4 and tested their specificity by qRTPCR against a panel of 45 human total RNAs." (PMID 21984916, 2011). "In both cell lines, 100 ng/mL of SS1P killed mesothelioma cells expressing mesothelin, in 20–50% of monolayers." (PMID 21305058, 2011). "Despite this, testing the cell line panel revealed that MSLN still appears to be a better marker of mesothelioma than LRRN4 and UPK3B." (PMID 21984916, 2011). "Mesothelin is highly expressed in mesothelioma, as well as ovarian cancer and lung cancer, and has been shown to be a biomarker for the diagnosis of mesothelioma." (PMID 21305058, 2011). "MSLN was detected in 15 of the 16 mesothelioma lines tested and for 13 of these the expression level was higher than that of the primary mesothelial cells." (PMID 21984916, 2011). "MM cell cultures expressed high mRNA levels of the mesothelioma markers mesothelin (MSLN), calretinin (CALB2), the WNT1 antagonist DKK1 and the stem cell marker BMI-1." (PMID 20175889, 2010). "By real time PCR we found that our cell cultures expressed high mRNA levels of typical mesothelioma markers as mesothelin (MSLN) and calretinin (CALB2), of BMI-1, a stemness marker and of DKK1, a potent Wingless [WNT] inhibitor." (PMID 20175889, 2010). "By real time PCR we found that our cell lines expressed high mRNA levels of typical mesothelioma markers as mesothelin (MSLN) and calretinin (CALB2), and of BMI-1, a stemness marker, and DKK1, a potent Wingless [WNT] inhibitor." (PMID 20175889, 2010). "Mesothelin is a cell surface protein that is found in normal mesothelium and highly expressed in several cancers including mesotheliomas and ovarian and pancreatic cancers." (PMID 19128473, 2009). "Mesothelin is the target protein of an immunotoxin-based therapy of mesotheliomas and ovarian and pancreatic cancers, of which the phase I clinical trial has been completed." (PMID 19128473, 2009). "Mesothelin is a 40 kDa protein present on the surface of normal mesothelial cells and overexpressed in many human tumours, including mesothelioma and ovarian and pancreatic adenocarcinoma." (PMID 19128473, 2009). "Mesothelin is a membrane bound glycoprotein expressed by mesothelial cells and over expressed in malignancy, especially mesothelioma." (PMID 19099560, 2008). "The most specific and sensitive markers for mesothelioma are mesothelin (in epithelioid mesothelioma), calretinin and cytokeratin 5/6." (PMID 19099560, 2008).
mesothelioma (continued). "Again, immunohistochemistry can help in the differentiation of mesothelioma and markers such as mesothelin, cytokeratin 5/6, calretinin, thrombomodulin and WT-1 have been used." (PMID 19099560, 2008). "Therefore, 90Y-mAb 22A31 is a promising RIT agent and supports the further development of C-ERC/mesothelin-targeted therapy for mesothelioma." (PMID 41901346, 2026). "The main TAAs in mesothelioma are mesothelin and the Wilms Tumor-1 (WT1) protein." (PMID 40918456, 2025). "Moreover, CTL responses have also been demonstrated against peptides from known mesothelioma biomarker proteins such as mesothelin and Wilms’ Tumor oncoprotein." (PMID 39921204, 2025). "Immunotoxins targeting mesothelin have attracted research interest in mesothelioma." (PMID 41375064, 2025). "Additionally, high MSLN-expressing mesotheliomas showed increased presence of collagen type I fibers, forming a dense collagen matrix that acts as a physical barrier limiting cancer dissemination." (PMID 41335396, 2025). "However, shed MSLN can be found in sera from EOC and mesothelioma patients and, thus, represents a potential antigen sink to MSLN-targeting therapies." (PMID 40402266, 2025). "Additionally, the blockage of MSLN with MUC16 by anti-MSLN antibodies can inhibit cancer cell expansion and metastasis and exert therapeutic efficacy in mesotheliomas." (PMID 40266223, 2025). "Of particular interest were peptides derived from mesothelioma biomarkers including mesothelin." (PMID 39921204, 2025). "However, the authors also observed a significant difference in the serum concentration of MSLN between stage 1 (2.09 ± 0.41 nM) and stage 2–4 (10.61 ± 3.89 nM) mesotheliomas." (PMID 41335396, 2025). "MSLN exhibits distinct expression patterns across different mesothelioma subtypes." (PMID 41400642, 2025). "In a study on mesothelioma and lung cancer cell lines, He and collaborators employed a PCR array approach to evaluate the changes in the expression of EMT-related genes caused by MSLN silencing." (PMID 41335396, 2025). "Although the role of mesothelin for screening or diagnosis of mesothelioma remains limited, it has been shown to correlate with disease status and may eventually play a role in monitoring response to treatment." (PMID 39409190, 2024). "However, this issue can be easily overcome by a simple strategy proposed by researchers: the screening of other mesothelioma-specific markers, such as podoplanin, cytokeratin, or mesothelin, which can help to differentiate lung carcinoma from mesothelioma." (PMID 38928369, 2024). "Mesothelin overexpression in mesotheliomas was detected, and we further compared its levels using qPCR between mesotheliomas and non-mesotheliomas using tumor tissues and clinical sample effusions, confirming its significance as a diagnostic biomarker for canine mesothelioma." (PMID 39315086, 2024). "Mesothelin, a protein with a suspected cell adhesion function in normal tissues, is overexpressed in significant subsets of patients with numerous cancer types, including mesothelioma, lung, pancreas, and CRC." (PMID 39174744, 2024). "Finally, given that dogs with mesotheliomas almost always present with effusion, mesothelin expression was analyzed using clinical effusion samples." (PMID 39315086, 2024). "Mesothelin is a peculiar molecule, as its expression is limited to only a few organs in health, with low expression found in the mesothelial tissues, whereas overexpression has been detected in mesothelioma." (PMID 39315086, 2024). "Mesothelin gene expression levels in major organ tissues (n = 24) and mesothelioma tissues (n = 4) were analyzed via qPCR relative to the housekeeping gene HPRT-1 to characterize mesothelin’s tissue distribution and assess its expression in canine mesotheliomas." (PMID 39315086, 2024). "Similarly, mesothelioma and colorectal cancer patients with high expression of MSLN are prone to chemotherapy resistance." (PMID 38628720, 2024).
mesothelioma (continued). "Mesothelin has attracted attention in human oncology as a promising candidate for a novel cancer immunotherapy target owing to its limited expression in healthy organs and its overexpression in mesotheliomas." (PMID 39315086, 2024). "In mesothelioma xenograft models, mesothelin-targeted TRuC (TC-210) T cells showed a more rapid reduction in tumor volume, enhanced infiltration into tumors, and faster activation and greater persistence in the tumor microenvironment compared to mesothelin-targeted CAR T cells." (PMID 38610930, 2024). "Canine mesotheliomas could be an ideal model for assessing mesothelin-targeted therapies for human mesotheliomas since canine mesothelin shares a similar expression pattern." (PMID 39315086, 2024). "Therefore, it is advised that IHC be used as a diagnostic assay to stratify and select eligible patients with mesothelioma for personalised anti‐MSLN therapies in future clinical trials." (PMID 37040900, 2023). "Different patient cohorts may also contribute to the variability, as MSLN is more likely to be expressed in epithelioid than sarcomatoid mesotheliomas." (PMID 37040900, 2023). "A recent clinical trial combining an anti-mesothelin CAR with PD-1-blockade indicates that both agents could act synergistically at least in mesothelioma." (PMID 36409438, 2023). "While these results are consistent with the prognostic data of MSLN expression in mesothelioma presented elsewhere, we recommend that they be validated in a prospective trial and the reliability of H‐score testing assessed to confirm the findings of this study." (PMID 37040900, 2023). "MSLN can be expressed in tumours that arise from these tissues, such as mesothelioma." (PMID 37040900, 2023). "As is the case with mesothelin, several approaches to targeting this protein for advanced solid tumors, including mesothelioma, are being explored; however, in contrast to mesothelin, it is also highly expressed in sarcomatoid tumors and represents a promising target for future therapy." (PMID 37296902, 2023). "Of interest, while an association of MSLN with improved prognosis is noted in mesothelioma, this relationship is not seen in all MSLN‐expressing diseases." (PMID 37040900, 2023). "Anetumab ravtansine, an anti‐mesothelin antibody conjugated to a maytansine derivative tubulin inhibitor, was recently investigated in a randomised, open‐label Phase 2 trial in mesothelioma." (PMID 37040900, 2023). "Although one study proposed that higher MSLN expression is associated with greater invasiveness in mesothelioma, as assessed by tumour T‐stage, that study did not include survival data." (PMID 37040900, 2023). "One of these antigens is mesothelin (MSLN), which is a glycoprotein overexpressed in mesothelioma, ovarian, and pancreatic carcinomas but low expressed on the surface of peritoneal, pleural, and pericardial cells, has become an attractive target for CAR T cell therapy." (PMID 36389701, 2022). "MSLN locus on chromosome 16 is especially enriched in ERV expression in mesothelioma (11 ERVs)." (PMID 36467966, 2022). "These patients could be directed to clinical trials and could benefit from new approaches to treating mesothelioma such as mesothelin targeted therapy, anti-angiogenesis therapy or immunotherapy." (PMID 35184730, 2022). "One intriguing study in which 11 mesothelioma patients who received preconditioning with cyclophosphamide followed by a single dose of mesothelin targeted CAR-T cells and at least three doses of anti-PD-1agent resulted in a 72% response rate and complete metabolic responses in two patients." (PMID 33824268, 2021). "The potential to use CAR-T therapy in mesothelioma has been explored fairly extensively, and pre-clinical models using various targets including mesothelin (MSLN), Fibroblast activation protein (FAP), Met Proto-oncogene (cMET), pan-ErbB and others have been extensively tested." (PMID 33952230, 2021).